PTCHD4 (patched domain containing 4)
Description:
Could act as a repressor of canonical hedgehog signaling by antagonizing the effects of SMO, as suggested by down-regulation of hedgehog target genes, including GLI1, PTCH1, and PTCH2 in PTCHD4-expressing cells.
Synonyms: C6orf138; PTCH53; SLC65C2; FLJ41841; dJ402H5.2
Tractability: Antibody: UniProt predicts a signal peptide or a membrane-spanning region; the Human Protein Atlas places it where antibodies can reach.
Gene: Protein-coding gene on chromosome 6 (47,856,673 to 48,111,197, reverse strand). Ensembl gene ENSG00000244694.
Subcellular location: Membrane
Subcellular location (Human Protein Atlas): Cytosol; Plasma membrane
Gene Ontology:
Cellular component: membrane
Genetic constraint (gnomAD): Loss-of-function variants: 33 observed, 59.74 expected, observed/expected ratio (o/e) 0.55, 90% interval 0.42 to 0.74. The upper end of that interval is the gene's LOEUF score, 0.74, which puts it in group 3 of 6, group 1 being the genes least tolerant of losing a copy. Missense variants: 1,058 observed, 1,072.7 expected, observed/expected ratio (o/e) 0.99, 90% interval 0.94 to 1.04. Synonymous variants: 478 observed, 430.37 expected, observed/expected ratio (o/e) 1.11, 90% interval 1.03 to 1.2.
Homologues: Orthologues: chimpanzee PTCHD4 (99% identical), macaque PTCHD4 (99% identical), rabbit PTCHD4 (98% identical), dog PTCHD4 (98% identical), pig PTCHD4 (98% identical), mouse Ptchd4 (97% identical), rat Ptchd4 (96% identical), guinea pig PTCHD4 (94% identical), tropical clawed frog ptchd4 (81% identical), zebrafish ptchd4 (74% identical), Drosophila melanogaster Ptr (24% identical), Caenorhabditis elegans ptr-17 (20% identical), and 4 more. Paralogues in human: PTCHD1 (50% identical), PTCHD3 (23% identical), PTCH1 (19% identical), NPC1L1 (18% identical), NPC1 (17% identical), PTCH2 (16% identical), DISP3 (15% identical), DISP1 (13% identical), DISP2 (12% identical), SCAP (10% identical).
Diseases named in the same sentence as PTCHD4 in open-access papers:
PTCHD4 is named in the same sentence as 6 diseases in open-access papers, as found by Europe PMC text mining. Sharing a sentence is not in itself a finding about the gene and the disease. The quoted sentences say what the papers report.
chronic obstructive pulmonary disease (1 paper, 2022). A chronic and progressive lung disorder characterized by the loss of elasticity of the bronchial tree and the air sacs, destruction of the air sacs wall, thickening of the bronchial wall, and mucous accumulation in the bronchial tree. "The two other DMRs were common with SBP: overlapping RNF141 and C6orf138 (PTCHD4), a gene found to be sensitive to transmitted adaptation to stress and associated with chronic obstructive pulmonary disease (COPD)." (PMID 36266660, 2022).
cutaneous melanoma (1 paper, 2022). A primary melanoma arising from atypical melanocytes in the skin. "In the cutaneous melanoma cell lines, MEL 04.01 and MEL 06.24, Nutlin-3 treatment increased significantly CDKN1A, CYFIP2 and PTCHD4 expression, whereas PIK3IP1 and MXD4 levels do not or hardly change." (PMID 36139642, 2022).
cardiovascular diseases (1 paper, 2022). "On the contrary, FAM72A, KYAT1, LRRC38, and PTCHD4 had little or no known associations with cardiovascular diseases so far although they are moderately expressed in the heart and may have unidentified functions in AF." (PMID 36078037, 2022).
PTCHD4 also shares sentences with these, for which no sentence is quoted: cancer (2 papers); COVID-19 (1); tumor (1).